TRAPPC2B (trafficking protein particle complex subunit 2B)
Description:
Prevents transcriptional repression and induction of cell death by ENO1. May play a role in vesicular transport from endoplasmic reticulum to Golgi.
Synonyms: MIP-2A; SEDLP1; TRAPPC2P1; MIP2A; SEDLP
Tractability: PROTAC: ubiquitination databases record sites on it.
Gene: Protein-coding gene on chromosome 19 (57,363,551 to 57,365,405, forward strand). Ensembl gene ENSG00000256060.
Subcellular location: Nucleus; Cytoplasm, perinuclear region; Endoplasmic reticulum-Golgi intermediate compartment; Cytoplasm
Subcellular location (Human Protein Atlas): Endoplasmic reticulum; Vesicles; Nucleoplasm
Gene Ontology:
Molecular function: protein binding; transcription corepressor binding; transcription regulator inhibitor activity
Biological process: positive regulation of gene expression; COPII vesicle coating; endoplasmic reticulum to Golgi vesicle-mediated transport; vesicle coating
Cellular component: endoplasmic reticulum; nuclear outer membrane; cytoplasm; endoplasmic reticulum-Golgi intermediate compartment; nucleus; TRAPP complex; TRAPPII protein complex; TRAPPIII protein complex; perinuclear region of cytoplasm
Genetic constraint (gnomAD): Loss-of-function variants: 5 observed, 8.04 expected, observed/expected ratio (o/e) 0.62, 90% interval 0.32 to 1.3. That is too few expected variants to judge how well the gene tolerates losing a copy. Missense variants: 160 observed, 166.4 expected, observed/expected ratio (o/e) 0.96, 90% interval 0.85 to 1.1. Synonymous variants: 45 observed, 53.73 expected, observed/expected ratio (o/e) 0.84, 90% interval 0.66 to 1.07.
Homologues: Orthologues: pig TRAPPC2 (98% identical), rat Trappc2 (98% identical), guinea pig TRAPPC2B (86% identical), Drosophila melanogaster Trs20 (57% identical). Paralogues in human: TRAPPC2 (100% identical), TRAPPC2L (26% identical).